CAT (catalase)
Diseases named in the same sentence as CAT in open-access papers (continued):
Sharing a sentence is not in itself a finding about the gene and the disease.
infection (continued). "The infection-induced upregulations were interestingly decreased in the case of moringa-fed groups, with the maximum reduction noticed in the 10% moringa and 48 h post-infection except for CAT which showed a slight increase after 48 h (p < 0.05)." (PMID 35812877, 2022). "However, with prolonged infection time, ROS accumulated excessively, and the organisms gradually increased the activities of SOD, CAT, and GPx can alleviate the damage caused by ROS." (PMID 36139883, 2022). "Interestingly, the treatment with catalase was able to abolish completely the H2O2 detection in both infection conditions." (PMID 35204161, 2022). "The improved antioxidant enzyme activities (SOD and CAT), digestive enzyme activities (trypsin, lipase, amylase, pepsin, and cellulose) could be connected with the enhanced resistance of fish against infection of V.harveyi." (PMID 36258024, 2022). "Acinetobacter baumannii is a catalase-positive Gram-negative bacterial pathogen that causes severe infections among compromised patients." (PMID 35402311, 2022). "Additionally, we support our proteome findings with phenotypic assays quantifying catalase and melanin production by C. neoformans over the duration of the infection models." (PMID 35862772, 2022). "Our results showed that infection of the rats with H. pylori caused a significant increase in lipid peroxidation, as revealed by an increased MDA concentration (p< 0.001), and a significant decrease in catalase activity (p< 0.001) in the stomach tissue." (PMID 36139826, 2022). "Similarly, infection with P. medicaginis increased the activities of CAT (p = 0.0047) and POD (p = 0.042) in alfalfa by 273.8 and 59.65%, respectively." (PMID 36845970, 2022). "Furthermore, the effects of infection by CAT-KO, HP1-KO, and RH strains on ROS production in mouse macrophages at a 2:1 ratio (tachyzoite: macrophages) were observed." (PMID 34163449, 2021). "In this study, ciliates were purified and cultured from G. columna tissues, and were then used to infect corals, so as to observe the changes in coral morphology, zooxanthellae, chlorophyll a, and mortality and to detect SOD and CAT to judge the stress response of corals after infection." (PMID 34827209, 2021). "Catalase activity was reduced in both varieties in response to the infection." (PMID 34638559, 2021). "We have previously shown that increased catalase activity was a characteristic feature of wheat plants treated with ET and infected with S. nodorum, being the cause of low H2O2 production in wheat at the early stages of infection." (PMID 33525389, 2021). "In particular, the bacilli exhibited differences in catalase/peroxidase activity, which could explain their different protective effects against infection." (PMID 33692195, 2021). "However, after infection with F. oxysporum, the CAT activity of the transformants was higher than that of the WT Pdpap in the same infection conditions." (PMID 34490017, 2021). "The maximum CAT activity occurred at the beginning of infection and then decreased." (PMID 35082814, 2021). "The greatest increase in CAT activity is due to the infection was observed in SMH87 leaves." (PMID 34299055, 2021). "Thus, mosquitoes with reduced oxidative burst had an expansion of viral load, while the enlargement of ROS production, via catalase silencing, decreases the infection prevalence." (PMID 34485182, 2021). "Infection with cucumber mosaic virus (CMV) also caused greater activity of catalase, peroxidase, and SOD in cucumbers, peppers, and tobacco plants, and greater activity of catalase, ascorbate peroxidase and SOD in cucumber and tomato plants." (PMID 34638559, 2021). "For microalgal hosts, similar to plant defense response, the expression of defense genes involved in the pattern recognition receptors, large heat shock proteins, and reactive oxygen scavenging enzymes (glutathione, ferritin, and catalase) were significantly upregulated during infection." (PMID 34884652, 2021).
infection (continued). "Importantly, and consistent with the proteomic analysis, significant increases in neutrophil elastase, myeloperoxidase, and catalase were observed on days 2 and 4 after infection, peaking on day 6 relative to controls." (PMID 34319784, 2021). "In addition, during infection, Phytophthora nicotianae increases its own peroxisomal catalase levels while concurrently down-regulating host catalase expression." (PMID 32174944, 2020). "In the 5th leaves, the infection-induced CAT activity increase was found only on the 5 dai." (PMID 32887449, 2020). "A general up-regulation of SOD, CAT, and ascorbate–glutathione cycle enzyme activities was found both for the whole-leaf extract and chloroplasts at the later stage of infection development (5–7 dai), except for APX which total activity decreased although the expression of cytAPX was increased." (PMID 32887449, 2020). "Furthermore, potent interactions have overcome the host antioxidant defense at the final stage of infection by tremendously reducing catalase, and superoxide dismutase activities." (PMID 32326009, 2020). "CAT was first induced at 2 dpi and its activity steadily increased with infection time." (PMID 33302873, 2020). "Several bacterial antigens such as BabA, SabA, OipA, AlpA, DupA, GGT, NAP, catalase, or Hsp60 are considered to be potential candidates for vaccines that might elicit both humoral and cellular immune responses during the infection." (PMID 33375694, 2020). "we noted a significant decrease in catalase activity at 8 and 16 days post-infection (dpi)." (PMID 32143731, 2020). "Similar to the initial phase of infection, bacteria responded by positive induction of expression of genes encoding the non-specific DNA-binding protein Dps, and catalase." (PMID 32517038, 2020). "CAT activity was slightly increased and then decreased sharply after inoculation (CPi), but what is interesting that CAT activity in KPhiPi samples significantly increased after 24 h infection by the pathogen." (PMID 32121090, 2020). "However, pretreatment with CLA178 significantly enhanced CAT activity at 6, 24 and 48 h after C58 infection." (PMID 33193244, 2020). "Moreover, in plants pretreated with CLA178, the CAT activity was significantly increased upon C58 infection at 48 hpi." (PMID 33193244, 2020). "It has also been reported that during plant-pathogen interaction, in a resistant plant, decreased catalase activity allows higher accumulation of hydrogen peroxide which prevents further pathogen infection by strengthening the cell wall, activating defense gene and hypersensitive cell death." (PMID 31568481, 2019). "Peroxidase/catalase (FTS_1471, KatG) is connected to resistance of Francisella against reactive oxygen species, it is secreted into culture media and into macrophages during infection where it restricts macrophage signaling and cytokine production." (PMID 31649645, 2019). "This indicated that these cotton miRNAs might play crucial roles in the VW pathogen infection by regulating the CAT genes." (PMID 30682777, 2019). "Moreover, the addition of catalase significantly attenuated the decrease in the ΔΨm values induced by D39 infection." (PMID 30984149, 2019). "In the compatible system, high activities of SOD, POD, and CAT were likely because these three antioxidant enzymes might play a role in ROS scavenging after infection by V26." (PMID 31906067, 2019). "This suggests that during infection E. amylovora may be releasing or actively secreting catalase to reduce damage done to cellular structures when peroxide production is elicited as a part of host-defense responses." (PMID 31849909, 2019). "A plausible mechanism for this drop could be due to reduced catalase activity in the mutant to counteract the oxidative burst from immune cells during infection." (PMID 31555608, 2019).
infection (continued). "The following six different parameters were identified: body weight gain 3–5 days post infection and catalase (CAT), superoxide dismutase (SOD), glutathione peroxidase (GSH-Px), malondialdehyde (MDA) and γ-interferon (IFN-γ) concentrations on the eight day post inoculation." (PMID 31698877, 2019). "However, ABA treatment significantly enhanced CAT activity in wild-type plants under PstDC3000 infection." (PMID 31126160, 2019). "Furthermore, the addition of catalase or infection with D39ΔspxB diminished the expression of these genes at 1 h." (PMID 30984149, 2019). "Therefore, the CAT activity decreased in the later stage of infection after inoculation with P. capsici." (PMID 30583543, 2018). "Different stress factors such as wounding, drought, pathogen infection and insect attack may induce similar responses, and we speculated that the significant decline in CAT activity over time in our study might be due to the same mechanism." (PMID 30559751, 2018). "It has been reported that the enhanced activities of CAT, SOD, and APX might be caused by pathogen infection in early infection stage to scavenge excessed ROS in harvested longans." (PMID 30386318, 2018). "Interestingly, post-infection fish fed with the MUT-supplemented diets had slightly higher expression of catalase than control and WT-fed groups." (PMID 30237797, 2018). "After infection, CAT activity in the OE lines was increased by 1.5 times over that in the WT." (PMID 30393539, 2018). "In addition, the activities of the enzymes catalase (CAT) and peroxidase (POD), which relate to the infection by pathogenic fungi, were determined." (PMID 30337932, 2018). "In the case of Aedes aegypti, altering redox homeostasis in the gut through catalase silencing reduced Dengue prevalence in the midgut, suggesting that ROS could antagonize infection by this specific arbovirus." (PMID 28379952, 2017). "Seventy-two hours post infection, the number of JG intracellular parasites for cultures treated with catalase was around 1.5 times lower than that obtained for control non-treated cultures, indicating a poorer intracellular development in a less oxidative environment." (PMID 28832582, 2017). "That the most infection-induced and most highly-expressed Ph. infestans catalase is secreted may suggest that its role is to eliminate H2O2 before it reaches the pathogen, or limit peroxide signaling within the plant." (PMID 29017458, 2017). "In addition, the effect of RNAi-mediated gene silencing of catalase, glutathione peroxidase, thioredoxin and protein oxidation resistance 1 in the control of infection with A. marginale was evaluated." (PMID 29258559, 2017). "Furthermore, the difference in survival between the WT/Wr strains and KO strain disappeared at 3 h after infection by addition of catalase." (PMID 28222125, 2017). "Infection by parasites was associated with an improved antioxidant defense system (CAT and GR) without oxidative damage, as confirmed by unaffected values of TBARS." (PMID 26938743, 2016). "In the present study, NE infection lowered CAT and GSH-Px serum activities." (PMID 26957116, 2016). "Also, inhibition of the catalase transcription (Solyc04g082460) suggests accumulation of SA in plant by RL under DC3000 infection." (PMID 25765075, 2015). "L. major infection did not cause any noticeable increase in the spleen CAT activity at different post-infection times." (PMID 25821293, 2015). "To confirm that UCH-L1 promotes pulmonary metastasis in vivo by altering H2O2 levels in the invasive cells, we examined whether UCH-L1-induced ROS generation is blocked by Adv-catalase infection in a MOI-dependent manner (10-50 MOI) in vitro." (PMID 25915537, 2015). "Moreover, the migration of B16F10 cells overexpressing UCH-L1 was significantly reduced after infection with Adv-catalase in a MOI-dependent manner." (PMID 25915537, 2015).
infection (continued). "However, midgut catalase and SODactivities were significantly lower 24 h after infection, indicating that P.vivax parasites can modulate the detoxifying response post-transcriptionally." (PMID 25742262, 2015). "Furthermore, A. fumigatus catalase was induced during early infection applying a murine model and in hyphae exposed to voriconazole or amphotericin B." (PMID 25661519, 2015). "Silencing of SlSRN1 increased accumulation of ROS in tomato leaves after infection with B. cinerea, which may be due to the changes in activity of superoxide dismutase and catalase induced by B. cinerea." (PMID 25010573, 2014). "On the other hand, the decrease of A. aquasalis catalase activity 24 hours after infection can be a consequence of the manipulation by the parasite to increase ROS, decrease the competitive microbiota and inhibit some immune pathways in order to improve its development inside the vector." (PMID 23441231, 2013). "Surprisingly, catalase knockdown exacerbated the infection of A. aquasalis by P. vivax." (PMID 23441231, 2013). "Also, the involvement of free radicals in the mosquito immunity was measured by silencing the catalase gene followed by infection of A. aquasalis with P. vivax." (PMID 23441231, 2013). "A significant increase in catalase expression was observed at 36 h after infection." (PMID 23441231, 2013). "In cells near infection sites the chloroplasts changed contrast, the intrathylakoid space and the matrix of the chloroplasts became electron dense, and peroxisomes containing crystals (probably high concentrations of catalase) were conspicuous." (PMID 23951305, 2013). "Here we showed that P. vivax initial infection decreased catalase activity and that catalase silencing increased the P.vivax parasites in the A. aquasalis midgut in a manner that apparently was not coherent with the model proposed of ROS-induced parasite killing." (PMID 23441231, 2013). "Catalase disruptants of Candida albicans are fully viable under normal culture conditions, but are extremely sensitive to oxidative stress by hydrogen peroxide and are cleared more rapidly than wild type cells in a murine infection model." (PMID 18927619, 2008). "However, the occurrence of cellular cytotoxicity limited the MOI of AdCat to 50 pfucell−1, which only produced a 3.5-fold increase in the activity of catalase in infected cells at the third day of infection compared to blank." (PMID 14647150, 2003). "In addition, infection decreased CAT activity in testosterone-treated males, probably because it could indirectly influence CAT expression by regulating T-cell and macrophage signaling pathways in the spleen." (PMID 40332798, 2025). "Furthermore, catalase activity was also reduced in infection with PA14." (PMID 38860823, 2024). "However, catalase and peroxidase activities and hormone SA level of chitosan‐sprayed plants were comparable or significantly higher than the unsprayed plants at the earlier timepoints at 1–4 days after infection." (PMID 37692128, 2023). "Multivariate logistic regression analysis showed that yeast infection, G. vaginalisinfection, catalase positivity, proline aminopeptidase activity, leucocyte esterasepositivity, and decreased L. acidophilus were independent risk factors forhr-HPV-positive infection (P<0.05)." (PMID 38827643, 2023). "Infection with A. solani caused enhancement in phenolics (77.21%), free proline (30.56%), malondialdehyde (30.26%), superoxide dismutase (SOD) (125.47%), catalase (CAT) (125.93%), peroxidase (POD) (25.07%) and polyphenol oxidase (PPO) (125.37%) compared to healthy plants." (PMID 36030517, 2022). "This is exactly what may have occurred in our case, due to P. indica-derived modulation, which primed an initial boosting of CAT activity in the early stages of infection, when the level of H2O2 was highest, and then resulted in increased AXP activity when H2O2 became less accessible." (PMID 34578118, 2021).
infection (continued). "However, both infection and pregnancy factors seem to influence CAT activity." (PMID 34019550, 2021). "Among them, two genes (FGSG_02881 and FGSG_06596) annotated as catalase (CAT), encoding one enzyme of detoxifying reactive oxygen species (ROS) in cells, were remarkably down-regulated when infected with soybean but the expression levels varied over infection time." (PMID 34072279, 2021). "In addition, the activities of CAT increased under ChiVMV infection." (PMID 32594157, 2020). "Also, an S. meliloti double‐mutant in two catalase‐encoding genes katB and katC has a symbiotic defect, but in contrast with exo mutants, it forms numerous infection threads that do not appear to fail until the time of S. meliloti release into symbiosomes." (PMID 31782853, 2020). "However, we observed an increased expression in cytochrome P450 and catalase genes that might indicate a response of the cells to the ongoing infection." (PMID 31533310, 2019). "Furthermore, the reduction in mtDNA copy number and mtDNA transcript level in D39-infected A549 cells was largely prevented by catalase pre-treatment, which is consistent with our data showing that catalase pre-treatment also decreased 8-OHdG levels in mtDNA after D39 infection." (PMID 30984149, 2019). "Four catalase enzymes (Sscle03g026200, Sscle04g037170, Sscle05g047950, and Sscle15g104430) were upregulated during infection, all showing highest expression at 96 hpi and no induction at 24 hpi, likely to coincide with peak ROS levels at the later stages of infection." (PMID 30808300, 2019). "The impact of catalase levels on the requirement for iron is likely to have a profound effect on C. albicans pathogenicity because iron homeostasis is tightly regulated during infection and efficient iron assimilation is essential for colonisation of iron limiting niches in the mammalian host." (PMID 28542620, 2017). "Moreover, activities of defense related enzymes (ascorbate peroxidase, guaiacol peroxidase, superoxide dismutase and catalase) induced due to CMV-infection were ameliorated with inoculation of B-30488, suggesting systemic induced resistance mediated protection against CMV in tobacco." (PMID 26934600, 2016). "Several catalase-peroxidase isoforms were identified in our study, which may scavenge ROS as well as combine with other ion transporters to play important roles in the Fusarium-induced infection of banana wilt." (PMID 25460190, 2014). "Therefore, catalase may participate in the elimination of ROS produced by F4 infection in banana root." (PMID 25460190, 2014). "Thus the GX-FBA predicted increase in catalase-peroxidase activity is in agreement with known fact that resistance to reactive oxidative species (ROS) produced by macrophages is critical for YP during initial stages of infection." (PMID 23216785, 2012). "Another example of a stress response gene is a highly expressed (11-fold increased expression at 2 dpi) secreted catalase-peroxidase (PITG_07143) that could act in counteracting the burst of reactive oxygen species (ROS) by the plant as a defense mechanism upon pathogen infection." (PMID 23251489, 2012). "The results of the present study demonstrated that in vivo infection of VRSA causes alteration of oxidant-antioxidant status in spleen, as evidenced by enhanced NO, MPO, MDA, PC, and GSSG level and decreased GSH level and also SOD, CAT, GPx, GR, and GST activity." (PMID 21785683, 2011). "Finally, C. albicans devoid of catalase was eliminated more efficiently in a mouse infection model." (PMID 19811500, 2010). "cinerea infection, peroxidase (POD) activity showed a progressive increase, while catalase (CAT) activity was significantly upregulated at 24 hpi and remained stable through 48 hpi." (PMID 42122852, 2026). "During E. labbeana-like infection, SOD and CAT activities are often significantly decreased in intestinal and other tissues compared to healthy controls." (PMID 41278479, 2025).